IL4 (interleukin 4)
Diseases named in the same sentence as IL4 in open-access papers (continued):
Sharing a sentence is not in itself a finding about the gene and the disease.
Allergy (continued). "C57BL/6 mice do not typically have a strong Th2 response in the CT allergy model and we did not see significant increases in IL-4 production among Tomato+ CD4+ T cells from allergy mice." (PMID 37191720, 2023). "No allergy-related inflammation of any kind has occurred (e.g., ‘interleukin-4 and interleukin-13 signaling’), as presented in S2 Fig, and S7 Table." (PMID 37053215, 2023). "Also, statistically significant relations for IL5 in infants with allergy and those with FA or ADFA, as well as for IL4 in patients with ADFA or FA+ADFA were observed." (PMID 37520545, 2023). "The expert panel consistently considered the use of anti-IL-4/IL-13 or anti-IgE appropriate overall, regardless of the presence of allergy in UAD patients." (PMID 37088840, 2023). "Similarly, it inhibits the expression of IL-8 in the cystic fibrosis bronchial epithelial IB3-1 cell line, and inhibits the expression of IL-4 in RBL-2H3 cells, which are commonly used in immunological experiments, inflammation and allergy." (PMID 37920212, 2023). "Our results showed that HPE could inhibit the production of IL-4, IL-6, IL-13 and TNF-α released by mast cells, thus, ultimately, compromised mast cell-mediated allergic diseases." (PMID 38012745, 2023). "With the rapid development of immunology, molecular biology, and biotechnology, many new biological drugs have been designed for the treatment of allergic diseases, including anti-immunoglobulin E (IgE), anti-interleukin (IL)-5, and anti-thymic stromal lymphopoietin (TSLP)/IL-4, to control symptoms." (PMID 36964157, 2023). "Indeed, a Mendelian randomization approach based on GWAS summary statistics indicates that several of these genes, including interleukin-4 (IL4) and IgE receptors (FCER1A, MS4A2), affect the incidence of allergic diseases." (PMID 36725846, 2023). "In the intracavitary space, cytokines such as IL-4 and IL-5 that are elevated in MPE and are central to the allergy cascade and may provide additional targets of therapy." (PMID 35222439, 2022). "These patients did not have a history of allergy and had more severe clinical symptoms and excessive secretion of IL-4 and IL-5 and overdifferentiation of Th0 cells into Th2 cells." (PMID 35531287, 2022). "Furthermore, the increased expression of IL-4 triggered allergic progression in RBL-2H3 cells, confirming that trifuhalol A can block their priming for further allergic reactions." (PMID 36077570, 2022). "An important issue that needs to be emphasized considering in vitro tests is the fact that cytokines are determined in various conditions and various diseases; however, only certain cytokines (i.e., TNF-α, IL-2, IL-4, IL-5, IL-6, IL-10, IL-13, and IFN-γ) are important in allergic reactions." (PMID 36590449, 2022). "Notably, AUF1s were also dispensable for the alternative polarization of macrophages by IL4, TGFβ and IL10, known to be engaged in allergic reactions." (PMID 35222366, 2022). "Some studies have indicated that the levels of IL-4 and effector T cells in patients with allergic diseases are significantly higher compared to patients without allergic diseases, while the levels of IL-10 and Treg are decreased." (PMID 36045965, 2022). "IL-4 secretion data from PBMC of these horses were subsequently analyzed by separating IL-4 concentrations from horses with long-term (>5 years) and short-term allergy (<5 years)." (PMID 34038479, 2021). "Interleukin (IL)-4, IL-5, and IL-13, mainly secreted by TH2 cells, are the critical stimulus that promotes serum IgE production and are crucial players in the development of allergic disease and wheezing." (PMID 34631611, 2021). "In naïve CD4+ T cells, which express a moderate level of GATA3 mRNA after receiving signals via the T cell receptors (TCRs) in the presence of IL-4, activated STAT6 proteins bind to the GATA3 gene locus, driving Th2 differentiation, which is a characteristic in the development of allergy." (PMID 33193294, 2020).
Allergy (continued). "Although the Th2 cytokine IL-4 is well known to play a critical role for the induction of immunoglobulin class switch to IgE and the development of food allergy, the prototypic Th1 cytokine IFN-γ can inhibit allergy by suppressing IL-4-induced IgE synthesis." (PMID 33362780, 2020). "Of note, cells producing both IL-4 and IL-10, but not IL-4+ IL-10− Th cells, were lost in this allergy model, in keeping with increased pathology." (PMID 32117317, 2020). "Consistent with the results described previously in patients with allergy 15, the proportion and absolute number of CD4+IL-4+Th2 and CD4+IL-17+Th17 cells were significantly higher in splenocytes and lungs of asthmatic mice than in those from normal or PBS group." (PMID 32549755, 2020). "Repetitive exposure to ODE did not induce an increase in the Th2 cytokines IL-4, IL-5, and IL-13 which are known to be involved in the classical allergy response and agrees with the lack of MyD88 involvement in regulating serum IgE levels." (PMID 32321514, 2020). "Bioinformatics analysis revealed that the capability to induce IL-4 was attributed to the tip region of the VP2 protein, wherein a higher number of predicted peptide segments on BTVs were positively correlated with the allergic reaction reported in cattle." (PMID 33375108, 2020). "In line with the protective effects that were observed on acute allergic symptoms and IgE, histone acetylation of Th2-related genes (GATA3, IL-4, IL-5, and IL-13) of splenocyte-derived CD4+ T cells after allergy induction was lower in raw milk-treated mice than in shop milk-treated mice." (PMID 31349704, 2019). "Our data corroborate the activation of IL4 in presence of PTGDR, which could have implications in allergic diseases." (PMID 30986261, 2019). "CNS2-active MPT cells are candidate cells that initially produce IL-4 to promote TH2 cell differentiation, and thus, they may be involved in allergy pathogenesis, although the mechanisms remain unclear." (PMID 29696026, 2018). "Release of IL-4 primarily regulates hyper-production of IgE, and expression of TNF-α and IL-6 stimulate the synthesis of acute phase response protein, which attenuates secretion of IgE and disruption of skin barrier function during allergic reactions." (PMID 28358324, 2017). "The results showed that the levels of IL-4 and IL-13 were higher in UC patients with FA than those UC patients without allergy." (PMID 27167186, 2016). "The TH2 cytokine IL-4 was also modestly, but not significantly, elevated in the allergy model in comparison to controls." (PMID 27445696, 2016). "In seasonal allergy, the Th2 cytokines TNF-α and IL-4 are elevated compared to Th1 cytokine levels." (PMID 23878502, 2013). "By contrast, T cells, which are the key cells expressing type-II cytokines in allergy, are not the major IL-4 producers in this innate immune context." (PMID 22702477, 2012). "IL-4 and IL5 with helper T-lymphocytes switch from type 1 to type 2, and subsequently high IgE secretion has been proved to be the cardinal pathogenesis of an allergic reaction." (PMID 22899954, 2012). "Peripheral blood mononuclear cells were isolated before and after the Spirulina feeding and levels of cytokines (interleukin-4 (IL-4), interferon-γ (IFN-γ) and interleukin-2), which are important in regulating immunoglobulin (Ig)E-mediated allergy, were measured." (PMID 18955364, 2011). "Their experiments addressed the importance of natural systemic levels of IL-4 in mice on tendon development, homeostasis and healing; such natural levels are notoriously low in the absence of allergy or other Th2 activation." (PMID 20537133, 2010). "IL-4 treatment in mice reduces iTreg cell frequency, highlighting that therapeutic approaches that target IL-4 or GATA3 might provide new preventive strategies facilitating tolerance induction particularly in Th2-mediated diseases, such as allergy." (PMID 18162042, 2007).
Allergy (continued). "Furthermore, the present findings underscore the neglected noncanonical pro-inflammatory role of IL-4 in microglia and broaden our understanding of the neuroimmune mechanisms in allergic diseases." (PMID 41019284, 2025). "In vitro and in vivo, evodiamine and rutaecarpine may inhibit the biosynthesis of allergy-related cytokines (TNF-α and IL-4) in mast cells and basophils, suggesting that they may be effective against IgE-induced allergic diseases such as atopic dermatitis and rhinitis." (PMID 39944619, 2025). "While we observed modulation in certain major cytokines associated with the development and regulation of allergies, such as IFN-γ and IL-13, we did not detect any modulation in the production of IL-4 and IL-17, which are also significant cytokines in allergic responses." (PMID 38538762, 2024). "In previous studies, WBGCT has antioxidant and anti-inflammatory effects by suppressing nitric oxide synthase, cyclooxygenase-2, cytokines, and interleukin-4 (IL-4), which may affect UACS-induced chronic cough related to airway inflammation and allergic reactions." (PMID 37893807, 2023). "Furthermore, anaphylaxis triggered by degranulation of mast cells is usually accompanied with elevated IL-4 and IL-1333 (which were not elevated in our study) rendering an allergic reaction rather unlikely in our cases." (PMID 35986144, 2023). "Notably in co-seasonal ASIT strongest negative correlation with allergy symptoms is with post challenge IgG2a/IgG1 which is stronger than IFN-γ/IL-4." (PMID 36439113, 2022). "This study indicated that type 2 helper T cell (Th2) response with IL-4–producing MCT type (high tryptase/PAR-2, low chymase/Ang II) significantly dominates in EPP cattle than in fascioliasis cattle, that is, suggesting that EPP cattle will be triggered by type I hypersensitivity (allergic disease)." (PMID 36605763, 2022). "Overall, horses suffering from allergy for more than 5 years trended towards higher IL-4 production after stimulation of their PBMC with anti-IgE or Cul allergen, while IL-4 secretion from PBMC of horses with short-term allergy resembled values of non-allergic horses." (PMID 34038479, 2021). "Chatila and colleagues showed that IL-4 can subvert Tregs to a pathogenic phenotype, expressing Th2 transcription factor GATA-3 as well as IL-4, a state which contributes to, rather than suppresses, allergic disease." (PMID 33362785, 2020). "YPFS has a certain effect on Th2-type cytokines such as (IL-4, IL-6, IL-10, and IL-17) and Th1 type cytokines such as (IFN-γ and tumor necrosis factor-α), and YPFS mainly exerts pharmacological effects such as immune regulation and anti-allergy and anti-inflammatory by acting on these cytokines." (PMID 31885639, 2019). "When considering the harmful effects arising from excess IL-4 and IL-13, in for example allergies, knowledge of the structural and functional characteristics of the IL-4 receptors and their unique signaling via STAT6 has been useful in efforts to therapeutically modify IL-4/IL-13 biology." (PMID 29930549, 2018). "Although all TFH cells may have the potential to secrete IL-4, one report has described polarized IL-4–secreting TFH cells in mice in the context of an allergic disease model, and it was suggested that these cells could subsequently differentiate into TH2 cells." (PMID 29984361, 2018). "On the other hand, previous research on the tumor microenvironment implied that M2 type macrophages could be subdivided into M2a, M2b, and M2c types, with the M2a type induced by IL4/13 and playing roles in the TH2 response, Type 2 inflammatory response, and allergies." (PMID 27589565, 2016). "The seemingly paradoxical finding that IL-4, a pro-allergic cytokine, reduces LPS-induced Eo/B CFU, may relate to reports suggesting an inverse relationship between eosinophilia and particular ratios of TH2 cytokines in allergic diseases." (PMID 24971469, 2014).
Allergy (continued). "In addition, both the increased IL-4 level and the decreased IFN-γ level in the soy protein group verified the Th1/Th2 imbalance resulting from allergy, while Lp–FOS might ameliorate soy protein-induced allergic reactions through modulating the imbalance of Th1/Th2." (PMID 39796399, 2025). "IL‐4 has well‐described effects on the polarization of Th2 cells, yet how Th2 cytokines modulate CLR expression in vivo and how this might contribute to the maintenance of allergic reactions and tissue remodelling, a major complication of allergy, remains unclear." (PMID 36114607, 2023). "Therefore, sustained upregulation of TLR4 in allergy may lead to pronged release of pro‐allergy factors (e.g., IL‐13 or IL‐4), rather than typical proinflammatory cytokines." (PMID 33900054, 2021). "Therefore, the significant decrease in IL4 in the HLH group compared to the HL group (p = 0.008) suggests that LL might reduce the transition of the chronic inflammation process from the innate to adaptive immunity, which also might involve the allergies." (PMID 33379227, 2020). "However, our findings that NK-4 inhibited IL-4 and IL-5 secretion by Th2 cells through down-regulating GATA-3 and NFATc1 mRNA expression suggest that NK-4 could be an effective strategy for the treatment of Th2-mediated allergic disease." (PMID 29933387, 2018). "Yet, the central role of such cells is debated because IL-4 production upon re-stimulation has been shown to be restricted to CD4+GATA3+ T cells in patients with known atopy, suggesting that the role of TH2 responses in IgG4-RD might be confounded by concomitant allergic disease." (PMID 28348556, 2017). "IL-4 promotes the development of Th2 cells and allergic inflammation so IL-4 increase may exacerbate ongoing allergy but can be suppressed by IL-10 and TGF-β regulatory cytokines; still further studies are needed to investigate B. integerrima influence on different types of allergy." (PMID 28031908, 2015). "Importantly, the inhibition of allergy cannot be attributed to a shift towards Th1 responsiveness, as it is well-established that H. polygyrus drives a strong Th2 response, and in our experiments no diminution in IL-4 production or IgE levels was observed." (PMID 20306466, 2010). "Along these lines, we specifically targeted the blood concentrations of eosinophilic granulocytes per se, the activity marker ECP and the chemokine IL-4 in blood in carefully characterized patients with COPD and chronic bronchitis but no allergy." (PMID 40391123, 2025). "Our findings did not align with the classical regulatory pattern of allergy development, where a reduction in IFN-γ typically coincides with the induction of IL-4, IL-13, and IL-17." (PMID 38538762, 2024). "Important for the context of allergic diseases is the fact, that CD38+ CD4+ T cells were characterized to be hypo-proliferative with a specific bias towards IL-13 secretion (with no change toward IL-4 or IL-5 secretion)." (PMID 38318168, 2024). "In addition, the up-regulation of GZMB expression by histamine in Th2-polarized CD4+ T cells, in CD4+ cells activated by IL-4 or in CD4+ T cells from AD patients indicates that this mediator of allergic inflammation may play a role in the homeostasis of the expression of GMZB in atopy and allergy." (PMID 37470818, 2023). "In this group, 9 (21%) subjects were considered to have non-allergic asthma in the standard allergy work-up, including SPT and serum IgE.8 patients (19%) who still would not qualify for anti-IgE, anti-IL4, or anti-IL5 treatment." (PMID 36294955, 2022). "Fifth, the influence of IL-4 combined with other genes (such as IL-6, IL-10, IL-17, IL-27, IFN-γ, etc.)or the environments on allergies has not been analyzed." (PMID 33834211, 2021). "In mice attenuation of OVA-induced allergy (IgE-specific Ig and OVA-induced IL-4) was seen using both mouse and human Ig mixtures, without effect on OVA serum IgG or OVA-induced IL-2." (PMID 32377529, 2020).
Allergy (continued). "In patients with allergies, some studies showed that, in BALF, IL-5 and IL-13, but not IL-4, levels increased when compared with those of healthy patients." (PMID 23283149, 2009). "While there are no ongoing trials of IL-4-related therapy in AIH, one could envision a future study, given the role of IL-4 in allergy and hypersensitivity." (PMID 41585412, 2024). "In a nonfood allergy model in which OVA-specific IgE is induced by injecting 2 doses of OVA plus Alum i.p., we also observed that OVA-specific IgE, but not IgG1, was severely impaired in Il4+/– mice, a result consistent with previously published observations." (PMID 39377224, 2024). "There were higher numbers of potential IL-4-inducing peptides, averaging 7.20 ± 0.748 segments (n = 20), in this VP2 tip region of allergic BTVs, compared to the 2.60 ± 0.800 segments (n = 15) (p < 0.01) recorded for BTVs without allergy records." (PMID 33375108, 2020).